MT-ATP6 (mitochondrially encoded ATP synthase membrane subunit 6)
Diseases named in the same sentence as MT-ATP6 in open-access papers (continued):
Sharing a sentence is not in itself a finding about the gene and the disease.
Leber hereditary optic neuropathy (7 papers, 2021 to 2024). Leber's hereditary optic neuropathy (LHON) is a mitochondrial neurodegenerative disease affecting the optic nerve and often characterized by sudden vision loss in young adult carriers. "Moreover, other less frequent mutations have been described in MT-ATP6 up to date, promoting a wide variety of clinical symptoms including Leber hereditary optic neuropathy (LHON)." (PMID 36674816, 2023).
Parkinson disease (7 papers, 2013 to 2026). A progressive degenerative disorder of the central nervous system characterized by loss of dopamine producing neurons in the substantia nigra and the presence of Lewy bodies in the substantia nigra and locus coeruleus. "Suspecting atypical Parkinsonism, a Wilson disease study and genetic tests of Charcot–Marie–Tooth (CMT), atypical Parkinsonisms (PARKs, GAB, DNAJC6, VPS13C, PINK, and LG), and atypical spinal–muscular atrophies (DYNC1H1, BICD, VAPB, GARS, DYNC1H1, mtATP6, and mtATP8) were carried out." (PMID 37510225, 2023).
Obesity (6 papers, 2014 to 2024). Accumulation of substantial excess body fat. "In the mitochondrial ATP synthase membrane subunit 6 (MT-ATP6) gene, essential for OXPHOS, two exonic variants (MT:8684C>T and MT:8664A>G) were found to associate positively with obesity risk, and one exonic variant (MT:8994G>A) was unique to the obese group." (PMID 39464187, 2024). "However, obesity caused a considerable increase in MT-ATP6 that is no longer observed in db/db mice." (PMID 36796135, 2023).
cardiomyopathy (5 papers, 2020 to 2025). A disease of the heart muscle or myocardium proper. "Intriguingly, the overlapping region of MT-ATP6 and MT-ATP8 seems to be a hotspot for mutations causing cardiomyopathy indicating that human heart is vulnerable to the dysfunction of mitochondrial ATPase." (PMID 31152278, 2020). "Prominently downregulated proteins (TUBGCP2, NPR2, MT-ATP6, SLC25A11, and so on) were enriched in cytoskeletal dynamics and cardiomyopathy pathways, while upregulated proteins (ATP6V0D2, HNRNPA1, TPM1, and so on) associated with oxidative stress responses and neurodegenerative disorders (AD and PD)." (PMID 40662159, 2025).
epilepsy (5 papers, 2016 to 2022). A brain disorder characterized by episodes of abnormally increased neuronal discharge resulting in transient episodes of sensory or motor neurological dysfunction, or psychic dysfunction. "We here characterized the epilepsy phenotype of patients with mitochondrial diseases due to MT‐ATP6 mutations." (PMID 33476484, 2021). "Validating the concept that these 28 epilepsy-like CYFIP1KD DEGs are good disease gene candidates, a post-analysis literature review determined that CACNA1C and MT-ATP6, although not included in our training set, are in fact known to cause epilepsy." (PMID 26824476, 2016).
Cognitive impairment (4 papers, 2021 to 2024). Abnormal cognition is characterized by deficits in thinking, reasoning, or remembering. "In the present study, we identified a novel MT-ATP6 variant (m.8777 T > C) in two unrelated patients presenting with an overlapping clinical phenotype dominated by adult-onset cerebellar ataxia, which comprises also severe visual and cognitive impairment." (PMID 38755691, 2024). "The mitochondrial coding and non-coding RNA are increased in the circulating extracellular vesicles in AD and mild cognitive impairment (MCI); the AD genes in the category of this study include MT-ND1-4,6, MT-ND4L, MT-ATP6, MT-ATP8, MT-CYB (or MT-CYBT), MT-CO1, and MT-RNR1." (PMID 36982253, 2023).
Mitochondrial myopathy (4 papers, 2021 to 2025). "Mutations in mitochondrial genes, such as MT-ATP6, and nuclear genes, such as MGME1 [MIM:615076] and RRM2B [MIM:604712], which are essential for mitochondrial function, can cause mitochondrial myopathy [MIM:500009], sometimes accompanied by ptosis." (PMID 40410591, 2025). "Moreover, a Krebs cycle anaplerosis with α-ketoglutarate in cybrids with a mutation in the MT-ATP6 gene and in a murine model of COX10−/− mitochondrial myopathy has demonstrated the ability to attenuate the alterations derived from mitochondrial failure." (PMID 37446148, 2023).
autism (3 papers, 2019 to 2025). Persistent deficits in social interaction and communication and interaction as well as a markedly restricted repertoire of activity and interest as well as repetitive patterns of behavior. "Differentially expressed ATP metabolism genes, such as that of the mitochondrially-encoded ATP synthase membrane subunit 6 (mt-ATP6), Atp2b2 and Abca5, are associated with neuropathologies/neurodegenerations, like Alzheimer’s disease and autism." (PMID 39715923, 2025).
developmental delay (3 papers, 2021 to 2025). "As other studies have reported, the clinical phenotype for SBG1-FB-MT-ATP6-T8993G was classic ‘LS’, while for SBG2-FB MT-ATP6-T8993G was ‘developmental delay, abnormal gait’; and for SBG3-FB-MT-ATP6-T9185C a mild myopathy and late disease onset." (PMID 34638685, 2021). "UDP1 (MT-ATP6) was a 4-year-old child who had intrauterine growth retardation, truncal hypotonia, microcephaly, global developmental delay, left ventricular noncompaction and Wolff-Parkinson-White syndrome." (PMID 40400026, 2025).
lactic acidosis (3 papers, 2021 to 2025). Metabolic acidosis characterized by the accumulation of lactate in the body. "Pyruvate was also increased in the MT-ATP6/PDH mutant organoids, correlating with the lactic acidosis expected in the organoids based on the patient phenotypes and the presence of the PDH mutation that hinders flux from pyruvate into the TCA cycle through acetyl-CoA." (PMID 35792828, 2022).
mitochondrial encephalomyopathy (3 papers, 2012 to 2024). A heterogenous group of disorders characterized by alterations of mitochondrial metabolism that result in muscle and nervous system dysfunction. "Three unrelated probands with mitochondrial encephalomyopathy harboring truncating MT-ATP6 mutations are reported." (PMID 32042910, 2020).
axonal neuropathy (2 papers, 2022 to 2024). Any nerve disorder affecting the axon of a nerve. "Over the last years, some authors reported purely axonal neuropathy associated with less severe mutations in other “mitochondrial genes”, e.g. for SCO2 or MTATP6." (PMID 38217609, 2024). "Mitochondrial diseases often present with fatal infantile phenotypes but over the last years some authors reported isolated axonal neuropathy phenotypes, e.g. for SCO2 and MTATP6." (PMID 38217609, 2024).
cataract (2 papers, 2022 to 2025). Partial or complete opacity of the crystalline lens of one or both eyes that decreases visual acuity and eventually results in blindness. "Among the upregulated Mendelian cataract disease-associated genes were several crystallins (CRYAB and CRYBB2) and mitochondrial encoded genes (MT-ATP6, MT-ND1, and MT-CO2)." (PMID 35348588, 2022).
COVID-19 (2 papers, 2024 to 2025). A disease caused by infection with severe acute respiratory syndrome coronavirus 2. "In conclusion, one novel mtDNA mutation was identified in this study, and some of the mutations identified in the MT-CYB as well as MT-ATP6 genes, including the novel mutation, are relatively common in the COVID-19 patient group." (PMID 40839580, 2025). "In conclusion, this study identified one novel mtDNA mutation, along with several relatively common mutations in the MT-CYB and MT-ATP6 genes among COVID-19 patients." (PMID 40839580, 2025). "This study aims to investigate mutations in the MT-CYB and MT-ATP6 genes of mtDNA in COVID-19 patients and their association with disease outcomes." (PMID 40839580, 2025). "In case of the MT-ATP6 gene, among the identified 8 mutations, the m.8744T > G mutation was higher in COVID-19-positive individuals than healthy controls (p = 0.009 < 0.05) and showed a significant correlation with the disease: OR (95% CI) = 24.04 (2.81–205.62)." (PMID 40839580, 2025).
Dystonia (2 papers, 2021 to 2025). An abnormally increased muscular tone that causes fixed abnormal postures. "In humans, the dystonia-linked ATP5MC3N106K mutation causes a reduction in ATP production and oxygen consumption, and MT-ATP6 mutations are linked to severe neurological conditions." (PMID 40904733, 2025).
IgA nephropathy (2 papers, 2016 to 2022). "Previous study of a patient with severe MT-ATP6 missense mutation and IgA nephropathy found strong mitochondrial fragmentation in a renal biopsy." (PMID 34635923, 2022). "Curiously, the patient studied here also had IgA nephropathy, which has also previously been linked to MT-ATP6 mutations." (PMID 34635923, 2022).
Immunodeficiency (2 papers, 2020 to 2024). Failure of the immune system to protect the body adequately from infection, due to the absence or insufficiency of some component process or substance. "The presented case extends the phenotypic spectrum of reported MT-ATP6 mutations by recurrent infections and immunodeficiency as a possible key symptom." (PMID 32527054, 2020). "In addition, new biochemical dysfunctions and disease symptoms have been added to the canonical phenotypic spectrum related to MT-ATP6 variants, such as carboxylase deficiency or recurrent infections and immunodeficiency." (PMID 38396915, 2024).
leprosy (2 papers, 2013 to 2023). Leprosy is a chronic infectious disease affecting primarily the skin and peripheral nervous system. "Other mRNAs were also less expressed in leprosy patients when compared to non-leprous samples, such as Bad, IL10, IL12 as well as several mitochondrial genes (mtCOX2, mtND1, mtND3 mtND5 mtATP6, and mtCYB)." (PMID 23798993, 2013).
MELAS (2 papers, 2021 to 2026). "Mutation load was higher in MT-ATP6-related LS than in MT-TL1-related MELAS (P = 0.008)." (PMID 41501912, 2026).
multiple sclerosis (2 papers, 2018 to 2022). A progressive autoimmune disorder affecting the central nervous system resulting in demyelination. "MT-ATP6/8 genes were also studied in otherneurodegenerative diseases such as Huntington,Friedreich’s ataxia and multiple sclerosis (MS)." (PMID 29845786, 2018).
myocardial infarction (2 papers, 2025). Gross necrosis of the myocardium, as a result of interruption of the blood supply to the area, as in coronary thrombosis. "MT-ATP6, a subunit of ATP synthase, is essential for mitochondrial ATP production and has been shown to exert protective effects against myocardial infarction and hyperlipidemia." (PMID 41142248, 2025).
ciliopathy (1 paper, 2021). A genetic disorder of the cellular cilia or the cilia anchoring structures, the basal bodies, or of ciliary function. "Variants in 16 genes were identified in probands suspected of ciliopathy and three with specific rare diseases, and a case with suspicion of mtDNA disorder was characterized with a pathogenic variant in the mitochondrial MT-ATP6 gene (MIM *516060)." (PMID 34448047, 2021).
congenital heart disease (1 paper, 2025). A heart disease that is present at birth. "MtDNA variants in the MT-ATP6 and MT-ATP8 genes have been indeed found in patients suffering from congenital heart disease as well as other multifactorial cardiovascular disorders." (PMID 39866453, 2025).
endometriosis (1 paper, 2021). The growth of functional endometrial tissue in anatomic sites outside the uterine body. "Second, we also excluded the MT-ATP6 gene with differential expression between groups (control and endometriosis) to comply with the NormFinder requirement." (PMID 33686153, 2021).
endothelial dysfunction (1 paper, 2025). In vascular diseases, endothelial dysfunction is a systemic pathological state of the endothelium (the inner lining of blood vessels) and can be broadly defined as an imbalance between vasodilating and vasoconstricting substances produced by (or acting on) the endothelium. "A hallmark of LKP-induced endothelial dysfunction was the significant downregulation of mitochondrial genes (e.g., mt-Co1, mt-Atp6) and upregulation of stress-response genes (e.g., Gsn, Fhl1)." (PMID 41459160, 2025).
gout (1 paper, 2018). A condition characterized by painful swelling of the joints, which is caused by deposition of urate crystals. "MT-ATP6 was significantly enriched for group-3 alleles in non-gout controls (25 of 104 (24.04%) controls, P = 1.14 × 10− 4, chi-square test)." (PMID 29976239, 2018). "MT-ATP6 was significantly enriched for group-2 alleles in patients with gout (10 of 52 (19.23%) patients had group-2 alleles in MT-ATP6, P = 9.03 × 10− 6, exact test)." (PMID 29976239, 2018). "In the non-gout controls, the MT-CYB region contained 69 alleles, followed by the MT-ND5 region (67 alleles; 3 mutant alleles were located in the overlapping MT-ATP6 and MT-ATP8 region)." (PMID 29976239, 2018). "When we categorized mutant alleles according to their positions in the mitochondrial genomes, 45 mutant alleles in patients with gout were located in the MT-ND5 region, followed-by the MT-CYB region (41 mutant alleles; 1 mutant allele was located in the overlapping MT-ATP6 and MT-ATP8 region)." (PMID 29976239, 2018).
Hearing impairment (1 paper, 2025). A decreased magnitude of the sensory perception of sound. "A systematic review further associated MT-ATP6 mutations with early-onset hearing impairment in children, highlighting ATP6 as a candidate for functional epigenetic regulation." (PMID 40689209, 2025).
Hürthle cell adenoma (1 paper, 2024). "Somatic mtDNA mutation 8697G > A of the MT-ATP6 gene was observed in Hürthle cell adenoma (HCA) and Hürthle cell follicular carcinoma (HCFC)." (PMID 39802950, 2024).
interstitial lung disease (1 paper, 2023). A diverse group of lung diseases that affect the lung parenchyma. "Recently, it was proposed that PMP-containing mtDNA (such as MT-ATP6) can promote the occurrence of interstitial lung disease in SSc patients by activating the inflammatory immune response of fibroblasts." (PMID 37373420, 2023). "Alternatively, it may be more effective to block the occurrence of interstitial lung disease in SSc patients specifically by sexually inhibiting the content of PMPs carrying a specific mtDNA (such as MT-ATP6) locally." (PMID 37373420, 2023).
invasive ductal carcinoma (1 paper, 2023). "The highest mutation rate/1000 bp was observed in the MT-ATP6 gene in both patients and the controls among the total of 30 pairs analysed by NGS and in the patients in the subset of 20 pairs with invasive ductal carcinoma (NST/NOS)." (PMID 36758048, 2023).
lupus erythematosus (1 paper, 2022). An autoimmune, connective tissue chronic inflammatory disorder affecting the skin, joints, kidneys, lungs, heart, and the peripheral blood cells. "SC-C5 expresses cell matrix markers (including mitochondrial gene MT-ATP6, ILI27, which is closely related to lupus erythematosus), and is rich in the process of extracellular matrix and axon regeneration." (PMID 36304995, 2022).
MERRF (1 paper, 2020). A mitochondrial encephalomyopathy characterized clinically by a mixed seizure disorder, myoclonus, progressive ataxia, spasticity, and a mild myopathy. "Consequently, we suggest truncating MT-ATP6 mutations should be excluded in patients presenting with a MERRF-like phenotype if genetic analysis for more well-recognized causes, such as the m.8344A>G mutation, are negative." (PMID 32042910, 2020).
metabolic acidosis (1 paper, 2025). "Our data demonstrated that MT-ATP6/8 defects present as a metabolic encephalomyopathy in early-onset patients, with 56% of infantile patients with MT-ATPase deficiency and 48% of pediatric patients with MT-ATPase deficiency experiencing episodes of metabolic acidosis." (PMID 40112238, 2025).
mood disorder (1 paper, 2024). A cognitive disorder a disturbance in which the person's mood is hypothesized to be the main underlying feature. "Patients with primary mtDNA mutations, such as G3460A (MT-ND1) and C9035T (MT-ATP6), have been reported to exhibit comorbidity with mood disorders." (PMID 40226710, 2024).
obsessive-compulsive disorder (1 paper, 2015). A disorder characterized by the presence of persistent and recurrent irrational thoughts (obsessions), resulting in marked anxiety and repetitive excessive behaviors (compulsions) as a way to try to decrease that anxiety. "The expression of other 5 protein-coding mitochondrial-encoded genes, MT-ND1, MT-ND5, MT-CO3, MT-ATP6, MT-ATP8, was found associated with the maternal psychopathology diagnosis of maternal obsessive compulsive disorder, maternal weight and with infant birth measures." (PMID 26418562, 2015).
prostate tumor (1 paper, 2019). "Altered expression of MT-CO2/COX2, and MT-ATP6 transcripts are significantly decreased in prostate tumor specimens [Gleason grade 5 (3 ± 2) to 8 (4 ± 4)] with a median of 7, and the downregulation pattern of MT-ATP6 genes further supports our TRAMP expression dataset." (PMID 30972102, 2019).
retinal disease (1 paper, 2004). "This is illustrated by the finding that the 15K retinome which comprises 15,645 transcripts including those which were solely found in a single study, contains an additional five of the 102 known retinal disease genes (RHOK, MTATP6, CHM, LRAT, RIMS1) not included in the 13K retinome." (PMID 15283859, 2004).
retinoblastoma (1 paper, 2023). A malignant tumor that originates in the nuclear layer of the retina. "MT‐ATP6 copies were equally abundant in AH from Controls (2065 copies per reaction; range 9–5822) and in AH from retinoblastoma patients (777 copies per reaction; range 26–58,489) (p = 0.7236)." (PMID 36148636, 2023). "Because of the high number of MT‐ATP6 copies and the low number of nuclear DNA sequence copies in Controls, the mitochondrial‐to‐nuclear DNA ratios in AH from Controls were significantly higher than those in AH from retinoblastoma patients." (PMID 36148636, 2023).
Sepsis (1 paper, 2024). Sepsis is defined as life-threatening organ dysfunction caused by a dysregulated host response to infection. "Notably, total bilirubin (TB), mt-CO1, mt-ND1, and mt-ATP6 levels were identified as independent risk factors for sepsis-induced mortality." (PMID 39113822, 2024). "Furthermore, we identified that the expression of mt-ND1, mt-CO1, and mt-ATP6 was associated with sepsis-related death, which had been confirmed by AUC under ROC calculations." (PMID 39113822, 2024). "Remarkably, in our study, mitochondrial function-related indicators, including mt-CO1, mt-ND1, and mt-ATP6, exhibited significantly higher discriminative capabilities for predicting the clinical outcomes of sepsis-associated lethality compared to traditional laboratory indicators." (PMID 39113822, 2024). "In comparison to other laboratory parameters, the expression levels of mt-CO1, mt-ND1, and mt-ATP6 demonstrate notable potential in predicting the prognosis of pediatric sepsis." (PMID 39113822, 2024). "Univariate analysis revealed a significant reduction in the expression of mt-CO1, mt-ND1, and mt-ATP6 in patients with sepsis." (PMID 39113822, 2024). "Notably, when compared to other laboratory parameters, the expression levels of mt-CO1, mt-ND1, and mt-ATP6 demonstrate promising potential for assessing the prognosis of pediatric sepsis." (PMID 39113822, 2024). "In the comparison between pediatric sepsis survivors and non-survivors, univariate analysis indicated a substantial reduction in the expression of mt-CO1, mt-ND1, and mt-ATP6 among non-survivors." (PMID 39113822, 2024).
sideroblastic anemia (1 paper, 2021). "To date, six genes have been discovered that may cause sideroblastic anemia: PUS1, YARS2, LARS2, TNRNT1, NDUFB11 and MT-ATP6." (PMID 34441767, 2021).
thyroid cancer (1 paper, 2018). "In addition, it has been demonstrated using yeast as model organism that two ATP synthase mutations accumulated during carcinogenesis (human MTATP6-P136S and MTATP6-K64E, found in prostate and thyroid cancer samples, respectively), are sufficient to help cancer cells to skip apoptosis." (PMID 30011966, 2018).